CTSS (cathepsin S)
Diseases named in the same sentence as CTSS in open-access papers (continued):
Sharing a sentence is not in itself a finding about the gene and the disease.
cancer (continued). "CTSS overexpression has been reported in various cancers, including HNC, breast cancer, and lung cancer." (PMID 40707961, 2025). "CTSS plays a key role in cancer progression, angiogenesis, and metastasis, particularly through its ability to degrade the ECM." (PMID 39712508, 2024). "This study demonstrates that the progression of cancer to later stages (stages III and IV) is associated with higher levels of serum CTSS compared to the early stages (stages I and II)." (PMID 39712508, 2024). "We demonstrated that the transient transfection of siRNA to knockdown CTSS in cancer cell lines led to the upregulation of 14 genes by approximately 1.5-fold." (PMID 38725007, 2024). "In human cancer cells, cathepsin S has been shown to participate in several processes, including angiogenesis, invasion and apoptosis." (PMID 39159189, 2024). "CTSS promotes cancer cell invasion through numerous mechanisms including ECM degradation, cleavage of cellular adhesion molecules and stimulation of angiogenesis." (PMID 37830980, 2023). "Studies on animal models of pancreatic cancer have demonstrated that CTSL and cathepsin S enzymes are released from cancer cells and act on the extracellular domain of cell adhesion molecules present on the surface of cancer cells." (PMID 38139037, 2023). "Cathepsin S contributes to several hallmarks of cancer including proliferation, angiogenesis, invasion and metastasis." (PMID 34572924, 2021). "Collectively, these results indicated that cathepsin S from human cancer cell lines cleaves membrane PAR2." (PMID 34572924, 2021). "When the mice developed cancer nociception, a single dose of the cathepsin S inhibitor, LY3000328, was administered." (PMID 34572924, 2021). "In a separate study, the combined depletion of cathepsin S in the cancer and macrophages was required to reduce the metastasis of breast cancer to the brain." (PMID 34572924, 2021). "The siRNA knockdown and overexpression by transient transfection with CTSS in cancer cell lines was performed and applied to gene expression profiling." (PMID 33754020, 2021). "Cathepsin S is a cysteine protease involved in the recruitment of immunosuppressive myeloid cells in cancer, including M2-like macrophages." (PMID 34845188, 2021). "In fact, the inhibition or deletion of the gene for cathepsin S reverses several hallmarks of cancer." (PMID 34572924, 2021). "Because cathepsin S inhibitors have been clinically used and show good safety profiles, we are considering a trial to test their efficacy for the management of cancer pain." (PMID 34572924, 2021). "A longitudinal study demonstrated that higher serum CTSS predicted higher risks of cardiovascular‐ and cancer‐specific mortalities." (PMID 32157804, 2020). "Reports have revealed that inhibition of cathepsin S induces autophagy in various types of human cancer." (PMID 29707130, 2018). "Collectively, these results reveal that the inhibition of cathepsin S sensitizes cells to apoptosis induced by various anti-cancer drugs through the calcium-mediated up-regulation of ER stress." (PMID 30120227, 2018). "Taeg Kyu Kwon at Keimyung University, Daegu, South Korea, and co-workers have demonstrated how inhibition of cathepsin S, which is expressed in many cancer cells, induces ER stress." (PMID 30120227, 2018). "Further, in one of the independent cohorts, the researchers found that cathepsin S was independently associated with CVD and cancer, and suggest future studies should evaluate cathepsin S’s potential clinical utility." (PMID 29379789, 2017). "In an earlier study, after transfecting human cancer cell lines HONE 1 with CTSS siRNA, LC3B-II protein was accumulated as determined by western blots." (PMID 27014637, 2016). "Elevated circulating cathepsin S concentrations predict mortality in elderly men and it has been linked to cardiovascular disease (CVD), type 1 and type 2 diabetes, cancer and inflammation." (PMID 25128296, 2014).
cancer (continued). "In cancer, cathepsin S is translocated from its normal intracellular lysosomal compartment into the extracellular milieu." (PMID 22168338, 2011). "We next examined the expression of cathepsin S on a panel of cancer cell lines (Colo205, LoVo, BxPC-3, Aspc-1 and Panc-1) by western blot." (PMID 22168338, 2011). "Enhanced cathepsin S expression and activity have been detected in several human cancers (glioma, breast, prostate, colorectal and pancreatic) with in vivo mouse models supporting its role in tumorigenesis." (PMID 22168338, 2011). "The results demonstrated that there was between 1765-6209 antibodies bound per cell (ABC) indicating a similar range of cathepsin S antigen density expressed on each cancer type assessed." (PMID 22168338, 2011). "Cathepsins B, cathepsin S, proteolytic enzymes, were thought to facilitate the breakdown of basement membranes thereby promoting cancer cell invasion into surrounding normal tissues." (PMID 21595995, 2011). "A number of groups have studied the mechanistic role of cathepsin S in cancer using in vitro and in vivo models." (PMID 22168338, 2011). "Given the frequent localization of lcp1-positive presumptive macrophages to the invasive edge of zebrafish ONP cancers, we assessed the relative expression of matrix metalloproteinases (MMPs) and cathepsins (CTSs) in precancerous and cancer microenvironments versus the control microenvironment." (PMID 39511408, 2025). "In addition, several cysteine cathepsins, including cathepsin S and cathepsin H, induce neovascularization to facilitate cancer growth." (PMID 38474423, 2024). "Similarly, CTSS was previously reported in cancer metastasis for its role of degrading extracellular matrix (ECM) proteins including laminin, fibronectin elastin, osteocalcin and some collagens." (PMID 36803413, 2023). "Previous studies have demonstrated the key role of CTSS in cancer cell invasion." (PMID 36803413, 2023). "CTSS featured prominently in our cancer risk analysis and, unlike TREX173,77, had not been implicated as a likely target for solid tumor immunotherapy." (PMID 37173324, 2023). "eQTLs related to CTSS and MHC class II genes featured prominently among the most informative features during model fitting, suggesting a role for class II antigen presentation in cancer risk." (PMID 37173324, 2023). "Cathepsin S (CatS) contributes to cancer progression by mediating autophagy." (PMID 35067006, 2022). "Given the strong link between inflammation and cancer, these results suggest that an increased production of pro-inflammatory cytokines, chemokines and Cathepsin S could contribute to B[a]P-driven carcinogenesis." (PMID 35336037, 2022). "We report here a role for cathepsin S in PAR2-dependent cancer pain." (PMID 34572924, 2021). "The cathepsin S/PAR2 axis is a strategic target for cancer pain." (PMID 34572924, 2021). "A potential concern with the inhibition of cathepsin S is that antigen processing, which is critical to the immune response to cancers, might be affected." (PMID 34572924, 2021). "This argument is countered by the finding that cathepsin S is upregulated by several cancers." (PMID 34572924, 2021). "It has been reported that secreted cathepsin B, cathepsin L and cathepsin S could cleave the cell adhesion molecule E-cadherin, promoting cancer cell invasion into the surrounding tissue." (PMID 33081056, 2020). "The loci that the CTSS gene is located on chromosome 1q21.2, which is amplified in many cancers and this amplification could contribute to elevated CTSS levels observed in clinical cancer samples, in addition to infiltrating CTSS-rich immune cells." (PMID 32398133, 2020). "Furthermore, serotonin receptor pathway helps in the regulation of the expression of cathepsin S (CTSS) and is highly expressed in several cancer subtypes in which it correlates with their progression." (PMID 33425733, 2020).
cancer (continued). "Further in silico gene expression analysis, using both in-house and publicly available datasets, confirmed these observations and suggested high CTSS expression may also be beneficial to outcome in ER-/HER2+ cancer." (PMID 31346333, 2019). "However, cathepsin S is also detected in malignant cells, and many researchers have suggested the pro-tumoral effects of cathepsin S in cancer cells." (PMID 30120227, 2018). "Taken together, our findings reveal that inhibition of cathepsin S is an inducer of ER stress; these findings may contribute to the enhancement of therapeutic efficiency in cancer cells." (PMID 30120227, 2018). "Multiple cancer cells highly express cathepsin S, which has pro-tumoral effects." (PMID 30120227, 2018). "CTSS is therefore an attractive target for cancer therapy to prevent disease progression." (PMID 28327651, 2017). "Cathepsin S (CTSS) is a lysosomal protease which has been shown to be expressed in a number of inflammatory conditions including autoimmune, cardiovascular disease and cancer." (PMID 27097645, 2016). "We hypothesize, that the development of small molecule CTSS inhibitor compound 6 will facilitate the understanding of mechanistic roles for CTSS in disease and furthermore, facilitate its characterisation in cancers which are currently poorly defined." (PMID 27097645, 2016). "In addition to being expressed in antigen-presenting cells, CTSS has recently been reported to be overexpressed in various malignant tumor cells." (PMID 26029922, 2015). "Thus, our findings provide innovative connective evidence between death autophagy and apoptosis, showing that mitochondria-dependent apoptosis is triggered by autophagy-regulated early ROS derived from XO in cancer cells treated with CTSS inhibitors." (PMID 26029922, 2015). "Cathepsin-S has recently been found associated with both cardiovascular and cancer mortality in the present cohort, although not including adjustment for biomarkers including troponin T and NT-proBNP and GDF-15." (PMID 24312445, 2013). "A significant amount of cell surface cathepsin S was detected in our panel of cancer cell lines." (PMID 22168338, 2011). "Based on the morphological and immunohistochemical differences between normal and cancerous hen ovaries, we hypothesized that expression patterns of the various CTSs related to cancer may differ between normal and cancerous tissues." (PMID 20727192, 2010). "Additionally, regarding the inflammatory aspect, several studies suggested that CTSS might contribute to the inflammation process in various diseases, including cancer." (PMID 39712508, 2024). "Additionally, this study was the first to unveil the association between CTSS levels and the proportions of HDL3a and HDL3b subclasses in NHL patients, which could play a pivotal role in the enhanced survival of cancer cells." (PMID 39712508, 2024). "Phenotype scanning revealed that seven out of the thirteen identified proteins (KDELC2, GSTP1, CTSS, CPNE1, ISLR2, SFTPB, and ICAM5) were associated with other traits, but none of these traits were likely to bias the associations between identified proteins and cancers." (PMID 37735436, 2023). "Thus, if we could prevent the activation of PAR2 by cathepsin S, we could potentially abrogate the sensitization of the receptors that mediate the nociceptive action of myriad mediators produced and secreted by cancers." (PMID 34572924, 2021). "The primary question addressed by the present study was whether cathepsin S produces cancer pain." (PMID 34572924, 2021). "Therefore, inhibition of cathepsin S may be an effective strategy for the enhancement of cell sensitivity to anti-cancer drugs." (PMID 30120227, 2018). "Therefore, cathepsin S is a promising therapeutic target for treating cancer." (PMID 30120227, 2018). "Thus, the application of cathepsin S inhibitors may have clinical utility in the treatment of cancer." (PMID 27097645, 2016).
cancer (continued). "Thus, CTSS activities have emerged as a potential therapeutic target for cancer treatment." (PMID 26029922, 2015). "However, specific CTSs are often upregulated in various cancers." (PMID 20727192, 2010). "Just like MMPs, cathepsins (CTSs) and a disintegrin and metalloproteinase (ADAM) are either over- or under-expressed in various cancer types, playing essential roles in cancer growth, progression, and metastasis." (PMID 40072103, 2025). "To investigate the role of CTSS in CRC progression, we assessed its expression in various cancer types." (PMID 40794185, 2025). "Therefore, CTSS could be a viable target for cancer treatment." (PMID 39712508, 2024). "We measured cathepsin S activity in HSC-3 cells and dysplastic oral keratinocytes (DOK, non-cancer cell line, cell number, 94122104, was from SIGMA-ALDRICH) with BMV157, the cathepsin S-selective probe, and BMV109, a pan cathepsin probe." (PMID 34572924, 2021). "Our results indicate that cathepsin S is activated in oral SCC, and that cathepsin S contributes to cancer pain through PAR2 on neurons." (PMID 34572924, 2021). "Among the CTSs, CTSB has been investigated most intensively and appears to play a role in cancer based on its increased expression in various human cancers." (PMID 20727192, 2010). "The findings identify CTSS as a novel enzyme for GSDMD cleavage and establish NIR‐pyroptosis as a non‐apoptotic anticancer modality, providing a promising opportunity to overcome apoptosis resistance in current cancer therapies." (PMID 40539828, 2025). "In addition, Cathepsin S and EGFR were also upregulated in cancer secretomes in comparison to control samples." (PMID 39743544, 2025). "The cancer paw volume was not different between mice generated with HSC-3 CTSS−/− or HSC-3 treated with random CRISPR/Cas9 or naïve HSC-3 cells." (PMID 34572924, 2021). "Fisetin (3,3′,4′,7-tetrahydroxyfavone), a naturally occurring flavonoid commonly found in plants is effective against cancer, and its possible mechanisms includes suppression of proliferation and metastasis of RCC through upregulation of MEK/ERK-Targeting CTSS and ADAM9." (PMID 32760434, 2020). "It included a number of genes with obvious cancer relevance including CD44, catenin b1 (CTNNB1), vimentin (VIM), cathepsins B and S (CTSB, CTSS), MMP9, XIAP, JunD, numerous proto-oncogenes (REL, YES, SET, FGR, CRK), and HSP90AA1 (which is a chaperone which stabilizes MIF as a client)." (PMID 28957348, 2017). "Altogether, our study not only identified a new biological role of CTSS in EGFR signalling regulation, but also provided a mechanical rationale to combine a CTSS inhibitor and an EGFR tyrosine kinase inhibitor for treating cancer through EGFR expression in the future." (PMID 27387133, 2016). "When not tightly controlled however, aberrant CTSS expression and activity have been demonstrated in a variety of pathologies, ranging from cardiovascular disease to respiratory conditions and cancer, marking it out as both a biomarker and potential therapeutic target." (PMID 38116078, 2023). "The human oral SCC cell line (HSC-3) with homozygous deletion of the gene for cathepsin S (CTSS) with CRISPR/Cas9 provoked significantly less mechanical allodynia and thermal hyperalgesia, as did those treated with LY3000328, compared to the control cancer mice." (PMID 34572924, 2021). "Although the role of cathepsin S in carcinogenesis and pain has been studied, the question of whether cathepsin S contributes to cancer pain has not been answered." (PMID 34572924, 2021). "Cathepsin S has been discussed as putative cancer target, but not in relation to CTCs." (PMID 30669448, 2019). "Mechanistically, cathepsin S mediates blood-brain barrier transmigration through proteolytic processing of the junctional adhesion molecule, JAM-B, and only the combined depletion of both MAM-derived and cancer cell-derived cathepsin S reduces the development of brain metastasis." (PMID 28210073, 2017).
cancer (continued). "Moreover, both CTSS and EGFR hold potential as therapeutic targets for cancer treatment." (PMID 27387133, 2016). "Moreover, the first demonstrated a positive correlation between CTSS levels and the proportion of anti-apoptotic subclasses HDL3a and HDL3b, which will enhance the understanding of disease mechanisms in NHL, potentially contributing to the development of new therapeutic strategies for this cancer." (PMID 39712508, 2024).